VDR (vitamin D receptor)
Diseases named in the same sentence as VDR in open-access papers (continued):
Sharing a sentence is not in itself a finding about the gene and the disease.
breast cancer (continued). "The effect of this SNP on breast cancer is plausible, given that the presence of the f allele in the 5′-promoter region of the VDR gene results in a protein that is three amino acids longer protein that the wild-type, and which is less transcriptionally active." (PMID 24769568, 2014). "VDR expression has been associated with better survival for colon and breast cancer." (PMID 25541970, 2014). "An electronic search was conducted of several databases, including PubMed, the Cochrane library, Web of Science, EMBASE, CBM and CNKI, for papers that describe the association between Fok1, poly-A repeat, Bsm1, Taq1 or Apa1 polymorphisms of the VDR gene and breast cancer risk." (PMID 24769568, 2014). "Laboratories investigations and epidemiological studies have suggested that the level of vitamin D, and the expression of the vitamin D receptor (VDR), might be associated with an increased risk of breast cancer." (PMID 24769568, 2014). "Therefore, additional functional experiments with vitamin D supplementation should be conducted on specific breast cancer subtypes and polymorphisms in the VDR gene and other gene variants." (PMID 24297042, 2014). "This study examines whether VDR gene polymorphisms are associated with breast cancer in these cohorts." (PMID 23554871, 2013). "We have investigated whether specific VDR gene polymorphisms are associated with breast cancer risk in Kazakhstan women." (PMID 29805854, 2013). "Population studies indicate that genetic variations in the VDR gene may affect breast cancer risk, particularly in premenopausal women." (PMID 23533810, 2013). "A nested case-control study within the Cancer Prevention study II (CPS-II) Nutrition Cohort examined the association between breast cancer and these four VDR SNPs (FokI, BsmI, ApaI, and TaqI), as well as SNPs in the 24-hydroxylase gene (CYP24A1) and vitamin D-binding protein gene (DBP)." (PMID 23533810, 2013). "Additional testing on the effect of varying genotypes on the functional mechanisms of the VDR could help to improve future testing and treatment of woman at risk for breast cancer." (PMID 29805854, 2013). "Decreased levels of VDR in breast cancer cells could be due to VDR gene polymorphisms, and/or DNA methylation." (PMID 23554871, 2013). "Epidemiologic studies have shown that low serum vitamin D levels correlate with increased risk of breast cancer, disease progression and bone metastases; while disruption of VDR signaling in the breast gland is associated with higher incidence of preneoplastic lesions." (PMID 22984610, 2012). "However, the fact that rs2239186 was associated with higher serum 25OHD levels in AA women as well as reduced breast cancer risk in this population is biologically coherent and reduces the likelihood of spurious findings for this VDR SNP." (PMID 22480149, 2012). "Previous studies on VDR polymorphisms and breast cancer risk have focused on only a few SNPs." (PMID 22480149, 2012). "Consistent with its essential role in vitamin D mediated effects on breast cancer, several polymorphisms in the VDR gene have been identified and their possible significance in breast cancer has been inconclusively assessed in epidemiological investigations across multi-ethnic groups." (PMID 21283672, 2011). "Additionally, the VDR was strongly associated with the oestrogen receptor positivity in breast carcinomas." (PMID 20831823, 2010). "Furthermore, studies with mice lacking VDRs have established that vitamin D participates in negative growth control of the normal mammary gland and that the disruption of VDR signaling is associated with accelerated mammary tumor development." (PMID 19442290, 2009). "In the subpopulation for whom there were data on serum 25(OH)D (1,391 cases and 1,365 controls), we further examined whether the association between the VDR genotypes and breast cancer risk differed by serum 25(OH)D level." (PMID 18419802, 2008).
breast cancer (continued). "Our results support potential effects of VDR polymorphisms on postmenopausal breast cancer risk." (PMID 18419802, 2008). "However, under the log-additive model, the haplotype FtCA (FokI F, TaqI t, VDR-5132 C and Cdx2 A) was significantly associated with breast cancer risk compared with the most common haplotype FTCG (OR = 1.43, 95% CI = 1.00 to 2.05)." (PMID 18419802, 2008). "Haplotype analysis revealed the haplotype FtCA (FokI F, TaqI t, VDR-5132 C, Cdx2 A), which contains the TaqI t allele, to be associated with a significantly greater breast cancer risk as compared with the most frequent haplotype FTCG (OR = 1.43, 95% CI = 1.00 to 2.05)." (PMID 18419802, 2008). "Vitamin D receptor (VDR) genotypes may influence breast cancer risk by altering potential anticarcinogenic effects of vitamin D, but epidemiological studies have been inconsistent." (PMID 18419802, 2008). "This is consistent with our finding of higher breast cancer risk for the TaqI t allele in ER-positive tumours, because less VDR mRNA and protein may result in less 1,25(OH)2D-VDR complexes and therefore in less anticarcinogenic activity." (PMID 18419802, 2008). "VDR polymorphisms have been widely studied in Caucasian populations in relation to breast cancer (BC) and malignant melanoma (MM) susceptibility, each finding different effects for SNPs, depending on the population analyzed and environmental factors acting upon them." (PMID 19105801, 2008). "The present study was undertaken to assess whether VDR polymorphisms BsmI and Poly(A) are associated with breast cancer risk in a large population-based case-control study of Caucasian and African-American women aged 35 to 64 years." (PMID 18067661, 2007). "This study provides additional support for an increased risk for breast cancer associated with the BsmI polymorphism at the 3' end of the VDR gene in postmenopausal Caucasian women and sheds light on the differential risk observed in menopausal status and race." (PMID 18067661, 2007). "Because of the key role that VDR plays in the vitamin D biosynthesis pathway, it has been hypothesized that polymorphisms within the VDR gene may modify the risk for breast cancer, either singularly or through gene-gene or gene-environment interactions." (PMID 18067661, 2007). "Gene-environment interactions may explain in part the inconsistencies in the association between VDR SNPs and breast cancer across studies." (PMID 17244366, 2007). "We conducted a nested case-control study within the Cancer Prevention Study II Nutrition Cohort of associations between breast cancer and four VDR single-nucleotide polymorphisms (SNPs), Bsm1,Apa1,Taq1, and Fok1, a poly(A) microsatellite, and associated haplotypes (baTL and BAtS)." (PMID 17244366, 2007). "To date, this is the largest study of VDR polymorphisms and breast cancer risk." (PMID 18067661, 2007). "Moreover, prior studies have focused on primarily Caucasian populations; hence, little is known about the association of VDR polymorphisms and breast cancer risk in African-American women." (PMID 18067661, 2007). "It is plausible that polymorphisms in the VDR gene could modify the effects of exposures such as vitamin D or calcium on breast cancer risk, although the specific mechanisms in humans are unknown." (PMID 17244366, 2007). "Vitamin D receptor (VDR) polymorphisms have been inconsistently associated with breast cancer risk." (PMID 17244366, 2007). "However, women with a calcium intake higher than the median were at lower breast cancer risk if they had the VDR Bsm1 bb, Taq1 TT, or the poly(A) long repeat (LL) genotype." (PMID 17244366, 2007). "Further investigations into the mechanisms of interactions of the VDR with other environmental and/or genetic influences to alter breast cancer risk may lead to a new understanding of the role of vitamin D in the control of cellular and developmental pathways." (PMID 11461072, 2001).
breast cancer (continued). "We have investigated whether polymorphisms in the VDR gene are associated with altered breast cancer risk in a UK Caucasian population." (PMID 11461072, 2001). "Furthermore, other studies have shown similar results, with nuclear VDR being associated with decreased breast cancer mortality for patients with Luminal B-like tumors and a positive association between VDR and a longer disease-free survival for patients with Luminal A tumors." (PMID 38612962, 2024). "However, the Fok1 VDR polymorphism was associated with ovarian and breast cancers in another study." (PMID 39335182, 2024). "Moreover, pre-diagnostic vitamin D levels and VDR interaction may influence breast cancer prognosis." (PMID 36014861, 2022). "Also PPARg physically associates with VDR in human breast cancer cells." (PMID 31141879, 2019). "Moreover, polymorphisms in the VDR gene have been linked to cancer risk, including prostate, breast, skin and bowel, and VDR expression has been linked to survival in prostate and breast cancer." (PMID 28301870, 2017). "Finally, VDR expression in breast cancer tissues may be inversely associated with the prognosis and survival of patients with breast cancer." (PMID 28460457, 2017). "Several VDR variants have been identified that may influence breast cancer risk." (PMID 26517870, 2015). "Moreover, VDR protein encoded by the F allele is more stable than the f isoform and is more effective in suppressing the oestrogen receptor signalling pathway and other pro-inflammatory pathways in breast cancer cells." (PMID 25887475, 2015). "Hence, findings from our study suggest that while the VDR-FokI f allele may play a role in early association with breast cancer development, the F allele may play a role on tumor progression and patient outcome." (PMID 23554871, 2013). "The findings on these VDR variants, together with significant differences in haplotypes between Cases and Controls suggest the potential need to screen for VDR polymorphisms in the context of breast cancer, particularly before considering Vitamin D supplementation." (PMID 23554871, 2013). "In a case (n = 928)-control (n = 843) study of breast cancer in AA and EA women, we measured serum 25OHD levels in controls and tested associations between risk and tag single nucleotide polymorphisms (SNPs) in VDR, CYP24A1 and CYP27B1, particularly by ER status." (PMID 22480149, 2012). "Although VDR rs10783218 was marginally associated with a twofold increased risk of ER+ breast cancer among EA women and VDR rs3819545 was associated with a decreased risk of ER- breast cancer, several SNPs in CYP24A1 were highly significantly associated with risk of ER- breast cancer." (PMID 22480149, 2012). "It is possible that the increased bone density observed in women with an increased risk of breast cancer may simply be a marker for high levels of vitamin D uptake, reflecting specific vitamin D receptor genotypes, or perhaps a marker of higher levels of endogenous estrogens." (PMID 18067661, 2007). "However, calcium intake appeared to modify the association of VDR SNPs with breast cancer risk." (PMID 17244366, 2007). "In breast cancer patients, AATBC was analyzed alongside VDR- and ESR1-associated lncRNAs, showing correlations with histological grade." (PMID 40724881, 2025). "In BT474 breast cancer cells, vitamin D can also derepress autophagy, with these cells expressing low levels of VDR." (PMID 40564179, 2025). "Reduced expression of VDR has been observed in many types of cancer, including breast cancer and colorectal cancer." (PMID 40630116, 2025). "The vitamin D receptor (VDR) has been implicated in the oncogenesis and prognosis of various tumors, but its relationship with molecular subtyping factors in breast carcinomas remains to be clarified." (PMID 40898467, 2025). "A significant relationship was found between VDR and ER, PR status, and the Ki-67 proliferation index in breast carcinoma cases." (PMID 40898467, 2025).
breast cancer (continued). "In our study, VDR expression was evaluated in preoperative biopsy specimens of patients who underwent surgery for breast carcinoma." (PMID 40898467, 2025). "Overexpression of the Vitamin D receptor (VDR) can prevent EMT in breast cancer cells co-cultured with macrophages." (PMID 39430253, 2024). "The current study was initiated to further elucidate the prognostic potential of VDR in breast cancer." (PMID 38612962, 2024). "The VDR protein levels were analyzed using immunohistochemistry in tumor samples from 878 breast cancer patients from Lund, Sweden, included in the Breast Cancer and Blood Study (BCBlood) from October 2002 to June 2012." (PMID 38612962, 2024). "The prognostic potential of VDR seemed to be confined to large and/or clinically detected breast cancers." (PMID 38612962, 2024). "A previous study has indicated that PTPN3 was overexpressed in breast cancer, and stimulates breast cancer growth through regulating vitamin D receptor (VDR) expression." (PMID 38173048, 2024). "In a review study, combining VDR agonists with standard treatment modalities like aromatase inhibitors has been proposed to enhance the treatment response in breast cancer." (PMID 38230221, 2024). "Malignant breast cancer cells have shown the downregulation of vitamin D receptor, limiting their responsiveness to the antitumor activity of vitamin D." (PMID 38732186, 2024). "In recent years, there have been clinical studies examining the use of VitD to activate VDR in various tumors, such as colorectal cancer, ovarian cancer, breast cancer, and prostate cancer." (PMID 38600588, 2024). "There are still several questions to be answered about the interplay between vitamin D, the vitamin D receptor, and how it can be of use in breast cancer prognostication and treatment." (PMID 38612962, 2024). "VDR genotyping of 1,017 breast cancer patients included 2002–2012 in Lund, Sweden, was performed using Oncoarray." (PMID 38351438, 2024). "Binding of PPARγ to the VDR has been reported for human T47D breast cancer cells and PPARγ-mediated inhibition of VDR-mediated transactivation for T47D and LNCaP cells." (PMID 39273194, 2024). "The cytoplasmatic or membranous expression of VDR has also been found in other tumors such as breast cancer and ovarian cancer." (PMID 38639057, 2024). "We know little about the effects and mechanisms by which intestinal epithelial VDR and the microbiome influence dysbiosis and the development of breast cancer." (PMID 37074210, 2023). "Together, these findings suggest vitamin D levels and VDR expression play an important role in breast cancer carcinogenesis." (PMID 37583424, 2023). "In 2020, we conducted a meta-analysis to evaluate the prognostic value of VDR expression in breast cancer." (PMID 37561808, 2023). "We were the first to report the potent interaction between quercetin and VDR, as well as an ameliorating effect of quercetin on breast cancer-induced hepatic inflammation and fibrosis." (PMID 37153919, 2023). "A recent study also reported higher VDR expression, associated with prolonged overall survival, in BRCA1-mutated breast cancers compared to sporadic breast cancers." (PMID 37345127, 2023). "Here, we tried to explore the possible link between tumor angiogenesis and liver injury and novel possible hepatoprotective effect of quercetin and its vitamin D mimicking action via VDR in breast cancer." (PMID 37153919, 2023). "In summary, more research is needed to elucidate the complexity of vitamin D signaling in both the normal mammary and tumor state to better understand the role of VDR in breast cancer prevention." (PMID 37583424, 2023). "Our study further suggests new therapeutic targets for restoring intestinal VDR and microbiome functions in preventing breast cancer (see the Graphical Abstract)." (PMID 37074210, 2023). "VDR hypermethylation has been associated with hepatocellular carcinoma (HCC), adrenocortical carcinoma (ACC), colorectal cancer, and breast cancers)." (PMID 38203278, 2023).
breast cancer (continued). "Vitamin D has been associated with a series of cancers (prostate, myeloma, colorectal, breast cancer), mediated through the vitamin D receptor (VDR)." (PMID 36900141, 2023). "We examined a 7,12-dimethylbenzanthracene (DMBA)-induced breast cancer model in intestinal epithelial VDR knockout (VDRΔIEC) mice with dysbiosis." (PMID 37074210, 2023). "For breast cancer, there are studies demonstrating a concurrent overexpression of VDR and RXRα, partially also describing a worse disease-free survival when RXRα is overexpressed." (PMID 36902107, 2023). "We then investigated the role of intestinal VDR in the development of breast cancer using a DMBA mouse model." (PMID 37074210, 2023). "The low expression of LRP2 in some breast cancers leads to a decrease in the activation of its nuclear receptor VDR, which promotes the proliferative process of breast cancer." (PMID 38037058, 2023). "In the literature search, we found that the prognostic value of VDR expression has been studied in a variety of tumours other than breast cancer, especially in digestive system tumours, such as oesophageal cancer, colorectal cancer, and pancreatic cancer." (PMID 37561808, 2023). "Because VDR expression is known to be inversely correlated with breast cancer aggressiveness, several recent preclinical studies have also investigated role of VDR in metastasis prevention." (PMID 37583424, 2023). "The study provides insights into the potential role of the gut microbiome in the pathogenesis of breast cancer and highlights the importance of VDR in maintaining gut and breast health." (PMID 37539732, 2023). "Two studies support the role of LRP2 in mediating endocytic uptake of vitamin D (in complex with vitamin D binding protein) and in the activation of vitamin D receptor signaling in breast cancer cells." (PMID 36980716, 2023). "Supporting the observed effects, the preventive and therapeutic effects of vit-D3 were detected in various cancers, including breast carcinomas with variable levels of VDR." (PMID 37835527, 2023). "In breast cancer cells, it has been demonstrated that these effects depend on the nuclear VDR expression." (PMID 36362766, 2022). "Upregulation of miR-214 diminished VDR-mediated signaling in breast cancer cell lines with a concomitant positive correlation between VDR level and an inhibitor of the Hedgehog pathway." (PMID 35328609, 2022). "Collectively, these data suggest an involvement of the GATA3-AS1 lncRNA in breast cancer pathogenesis through vitamin D3/VDR signaling." (PMID 35328609, 2022). "The results of research on breast cancer cell lines should be interpreted considering the high heterogeneity of breast cancer cases and different forms of VDR, as well as pleiotropy of biological action of vitamin D." (PMID 35328609, 2022). "A series of studies have examined the action of VDR agonists on putative breast cancer stem or progenitor cells identified by some markers (CD44hi/CD24low and/or ADH1+) that can grow as floating, nonadherent spheres (mammospheres)." (PMID 35406059, 2022). "Appraisement of vitamin D receptor (VDR) polymorphisms is thought to be crucial to detect and make approaches targeting groups at risk for breast cancer (BC)." (PMID 35983446, 2022). "Previous research suggests associations between low systemic levels of vitamin D and poor breast cancer prognosis and between expression of the vitamin D receptor (VDR) in breast cancers and survival." (PMID 36014861, 2022). "Collectively, our results confirm ERRα as a master regulator of oncometabolic and proliferating signals in breast cancer, and provide insights into the molecular mechanisms underpinning VDR genomic and antitumor action in advanced breast cancer." (PMID 34003583, 2022). "Several other studies have shown the important role of the vitamin D3/VDR axis in breast cancer pathogenesis." (PMID 35328609, 2022). "The expression of VDR was evaluated immunohistochemically in a tissue microarray of subsequent breast cancers." (PMID 36014861, 2022).